MTRF1L (mitochondrial translation release factor 1 like)
Description:
Mitochondrial peptide chain release factor that directs the termination of translation in response to the peptide chain termination codons UAA and UAG.
Synonyms: MTRF1A; HMRF1L; MRF1L
Tractability: Small molecule: a structure with a bound ligand is known. PROTAC: ubiquitination databases record sites on it; its protein half-life has been measured.
Gene: Protein-coding gene on chromosome 6 (152,987,362 to 153,002,709, reverse strand). Ensembl gene ENSG00000112031.
Subcellular location: Mitochondrion
Pathways (Reactome):
Metabolism of proteins: Mitochondrial translation termination
Gene Ontology:
Molecular function: translation release factor activity; translation release factor activity, codon specific
Biological process: mitochondrial translational termination; translational termination
Cellular component: mitochondrion; mitochondrial matrix
Genetic constraint (gnomAD): Loss-of-function variants: 22 observed, 25.5 expected, observed/expected ratio (o/e) 0.86, 90% interval 0.62 to 1.23. The upper end of that interval is the gene's LOEUF score, 1.23, which puts it in group 5 of 6, group 1 being the genes least tolerant of losing a copy. Missense variants: 379 observed, 391.6 expected, observed/expected ratio (o/e) 0.97, 90% interval 0.89 to 1.05. Synonymous variants: 137 observed, 148.4 expected, observed/expected ratio (o/e) 0.92, 90% interval 0.8 to 1.06.
Homologues: Orthologues: chimpanzee MTRF1L (98% identical), macaque MTRF1L (96% identical), dog MTRF1L (88% identical), pig MTRF1L (87% identical), mouse Mtrf1l (80% identical), rat Mtrf1l (80% identical), tropical clawed frog mtrf1l (66% identical), zebrafish mtrf1l (54% identical), Drosophila melanogaster mRF1 (41% identical). Paralogues in human: MTRF1 (44% identical), MRPL58 (14% identical).
Diseases named in the same sentence as MTRF1L in open-access papers:
MTRF1L is named in the same sentence as 3 diseases in open-access papers, as found by Europe PMC text mining. Sharing a sentence is not in itself a finding about the gene and the disease. The quoted sentences say what the papers report.
ovarian carcinoma (1 paper, 2023). A malignant neoplasm originating from the surface ovarian epithelium. "The differential expression of CCDC170, MTRF1L, ZBTB2, ARMT1, PLEKHG1 and QRSL1 genes affected the overall survival (OS) of ovarian cancer patients." (PMID 37024829, 2023).
tumor (2 papers, 2023 to 2025). "In the later stage, clinical samples or animal model experiments can be utilized to verify the expression level of the MTRF1L in tumor versus normal tissue." (PMID 40620061, 2025).
cancer (1 paper, 2025). A tumor composed of atypical neoplastic, often pleomorphic cells that invade other tissues. "The study of SCP2, ABCD3, MICOS10, GCDH, and MTRF1L genes' immune infiltration and cancer correlation in CRC offers a fresh perspective." (PMID 40620061, 2025). "Additionally, cell experiments will be conducted to observe the impact of MTRF1L knockout or overexpression on cancer cell proliferation, migration, and invasion abilities, further elucidating its role in cancer." (PMID 40620061, 2025).